PENK (proenkephalin)
Diseases named in the same sentence as PENK in open-access papers (continued):
Sharing a sentence is not in itself a finding about the gene and the disease.
ischemia (1 paper, 2007). A hypoperfusion of the BLOOD through an organ or tissue caused by a PATHOLOGIC CONSTRICTION or obstruction of its BLOOD VESSELS, or an absence of BLOOD CIRCULATION. "Several genes display a particularly impressive shift: Proenkephalin is 44-fold more abundant in CA1 in the native state, but looses this strong preference in ischemia (only 3-fold more abundant in CA1)." (PMID 17937787, 2007).
ischemic stroke (1 paper, 2024). A stroke disorder caused by obstruction of blood flow to the brain, due to thrombotic (local blood clot formation) or embolic (due to a blood clot or other material traveling from another site) event. "PENK has been shown to be elevated in ischemic stroke, correlating with the severity of brain injury, and may predict mortality in the acute phase of ischemic stroke." (PMID 39518330, 2024).
lung small cell carcinoma (1 paper, 2021). "For example, although the lung equivalent of PENK has not been identified, PENK perhaps could also induce lung small cell carcinoma to differentiate by down-regulating scTF." (PMID 34911496, 2021).
melanoma (1 paper, 2022). A malignant, usually aggressive tumor composed of atypical, neoplastic melanocytes. "Keratinocytes are expressing enkephalins, or opioid receptors (ORs), belonging to G protein-coupled receptors, while low levels of enkephalin and proenkephalin (PENK) have been detected in melanomas." (PMID 35334544, 2022).
migraine (1 paper, 2019). "Several previous studies have shown that peptides from prohormones such CGRP (in plasma and TG), NPY (in dorsal root ganglia and DH), and PENK/POMC (in H) are directly associated with migraine and other pain states." (PMID 31649062, 2019). "Using this approach, a total of 6 prohormones were found to correlate with migraine and/or OIH conditions from their respective controls: Vasoactive Intestinal peptide (VIP), PACAP, thyrotropin-releasing hormone prohormone (proTRH), PENK, SCG and proSAAS." (PMID 31649062, 2019). "Specifically, for migraine: VIP and SCG2 in the NAc, PACAP, SCG1, and proTRH in the PAG, and PENK in the DH; and for OIH: VIP in the NAc, SCG, proSAAS and PACAP in the PAG, and SCG in the TN and DH, were significantly changed between the treated and control groups (p ≤ 0.1) in both cohorts." (PMID 31649062, 2019). "Intriguingly, six precursor proteins (determined by the overlap between protein classes among treatment groups from PANTHER analysis) were common to both migraine and OIH treatments in both cohorts, and include SCG, PENK, proCGRP, VGF, and Peptidyl-prolyl-cis-trans-isomerase-A." (PMID 31649062, 2019).
neuroblastoma (1 paper, 2018). Neuroblastoma (NB) is the most common solid, extracranial childhood tumor. "Processing of proenkephalin and pro-NPY precursors by cathepsin V has been demonstrated in human neuroblastoma cells in vitro." (PMID 29998195, 2018).
neuropathic pain (1 paper, 2015). Chronic pain caused by damage to nerve fibers. "In the rodent CCI neuropathic pain model, an increase in paw withdrawal latencies to mechanical and thermal stimulus following application of recombinant defective herpes simplex viral vector encoding proenkephalin has been reported." (PMID 25563474, 2015).
neuropathy (1 paper, 2020). A disorder affecting the nervous system that manifests with pain, tingling, numbness, and/or muscle weakness. "Altogether, we posit that the demonstrated changes in gene expression of the opioid propeptides and their respective receptors, i.e., PENK and DOP receptor vs. PDYN and KOP receptor, in neuropathy induced by sciatic nerve injury, may exert opposite influence on pain perception." (PMID 32026358, 2020).
Obesity (1 paper, 2022). Accumulation of substantial excess body fat. "Our study suggests that adipokines such as PENK, IGF-1, chemerin, AGF, AFABP and leptin might affect the development of obesity by directly modifying individual eating behavior." (PMID 34636987, 2022).
obstructive jaundice (1 paper, 2019). A finding indicating increased bilirubin levels in the blood and urine, due to intrahepatic or extrahepatic obstruction of the biliary system. "Importantly, proenkephalin mRNA level in the skin was increased both in patients with obstructive jaundice and rat models of cholestasis." (PMID 31350433, 2019).
proteinopathies (1 paper, 2022). "However, apart from sCJD patients, decreased or a trend towards decreased CSF PENK levels were also previously reported in HD, AD, FTD and DLB, suggesting a common pathogenetic pathway in most proteinopathies." (PMID 35216166, 2022).
psychostimulant addiction (1 paper, 2018). "Similarly, it is likely that genetic variations in the endogenous PENK gene influence the development of behavioral and neurobiological adaptations in response to psychostimulant exposure, and thus modify vulnerability to psychostimulant addiction." (PMID 29892236, 2018).
septic shock (1 paper, 2024). Shock caused by infection; frequently caused by gram negative bacteria, although some cases have been caused by other bacteria, viruses, fungi, and protozoa; characterized by fever, chills, tachycardia, tachypnea, and hypotension. "In particular, in the subgroup of patients with septic shock, PENK concentrations were 199.7 (101.7–304.3) pmol/L when AKI was present and 117.6 [80.6–209.6] pmol/L in the absence of AKI, yet this difference was not statistically significant (p = 0.2128)." (PMID 38790966, 2024).
substance abuse (1 paper, 2021). The use of a drug for a reason other than which it was intended or in a manner or in quantities other than directed. "Some of us previously investigated involvement of eight genes in the opioid system (OPRD1, OPRK1, OPRL1, OPRM1, PDYN, PENK, PNOC, and POMC) and their potential effects on substance abuse." (PMID 34440333, 2021).
cancer (29 papers, 2005 to 2025). A tumor composed of atypical neoplastic, often pleomorphic cells that invade other tissues. "Among the candidates is the hormone PENK and the down-regulation of PENK expression in cancer suggests a possible association with cancer development." (PMID 16343351, 2005). "When transfected into LuCaP 70CR, PENK up-regulated the expression of adenocarcinoma antigen AGR2, a marker associated with cancer cell differentiation." (PMID 34911496, 2021). "Thus, PENK could reverse cancer de-differentiation caused by scTF reprogramming." (PMID 34911496, 2021). "Despite that, VIM and PENK were excluded from the following analysis because only very few cancer patients had VIM or PENK hypermethylation." (PMID 27891190, 2016). "Recently, a Phase I clinical trial of HSV-mediated gene transfer of proenkephalin to the DRG was reported to produce significant pain relief in patients with cancer pain." (PMID 25563474, 2015). "Both PENK and CNTN1 have been detected in the prostate in other studies, and cancer down-regulation of PENK was evident in published datasets." (PMID 19737398, 2009). "Obtained results confirm that a combination of biomarkers selected produces better results for Stage I & Stage II detection than CA-62 cancer marker alone (AUC 0.990 vs 0.973) and other previously proposed panel of markers containing PENK, pro-SP, hGH and CA15-3 (AUC = 0.785)." (PMID 40458730, 2025). "Third, not only stem-like cancer cells but also luminal-like cancer cells could respond to PENK signaling." (PMID 34911496, 2021). "We suggest that PENK could likewise be effective in promoting cancer differentiation of a solid tumor." (PMID 34911496, 2021). "We observed this inhibition in our reprogramming of prostate stromal cells, in which we were able to obtain stem-like cells from PENK-negative cancer-associated stromal cells but not PENK-positive benign tissue stromal cells." (PMID 34911496, 2021). "Second, if PENK could affect stem-like cancer cells it might also reverse reprogramming of scTF-transfected luminal-like cancer cells." (PMID 34911496, 2021). "The cancer-associated stroma of prostate tumors was found to have no expression of PENK as found by immunostaining, expression analysis of microdissected tumor tissue samples, and dataset query of sorted CD90+ cancer-associated stromal cell transcriptomes." (PMID 34911496, 2021). "With further research, it is possible that PENK plus other stromal factors could induce cancer cells to a pseudo-normal state (as shown by our experiments with stromal induction of NCCIT)." (PMID 34911496, 2021). "PENK has been identified as a key gene in multiple types of cancers." (PMID 32334633, 2020). "We selected si-PENK-1 for the subsequent CCK-8 assay to determine whether si-PENK affects OS cancer cell proliferation." (PMID 32334633, 2020). "PENK is expressed in several cancers and performs diverse biological functions." (PMID 32334633, 2020). "Previously, we showed that expression of prostate-specific PENK was down-regulated in cancer." (PMID 19737398, 2009). "We hypothesized that cancer could be due to defects in stromal/epithelial interaction, and expression of genes like PENK could be altered in cancer." (PMID 16343351, 2005). "Immunohistochemistry results indicated significantly elevated GALP, CACNA1C, COL16A1, PENK, C4BPA, PSMA2, and CXCL9 expression in cancer tissues." (PMID 38481252, 2024). "Immunohistochemistry results indicated significant upregulation of GALP, CACNA1C, COL16A1, PENK, C4BPA, PSMA2, and CXCL9 in cancer tissues." (PMID 38481252, 2024). "In this manuscript, we reported an extended study on the growth suppression of multiple cancer cell lines with ligands derived from CD36+ fibroblasts or an agonist for one of the ligands, PENK." (PMID 36361532, 2022).
cancer (continued). "It is possible that STC1 and PENK could act in concert towards differentiation, with additional contribution from many other differentially expressed candidate genes between CD49a+ prostate and CD13+ bladder stromal cells, between CD49a+ prostate stromal and CD90+ cancer-associated stromal cells." (PMID 34911496, 2021). "We showed the potential of NPY, PENK, and WIF1 as combined epigenetic markers for CRC diagnosis, both in tissue and serum and tested their use as serum biomarkers in other cancers." (PMID 24289328, 2013). "Among them, three genes (DMC1, PENK, and SIM2) were selected for further independent validation with additional normal tissues and BCa tissues because the genes showed higher methylation levels in all cancer tissues than in normal tissues." (PMID 36403035, 2022). "Conditioned media of STC1+PENK− cancer-associated stromal cells (isolated from a Gleason 3 tumor) were still able to induce NCCIT to down-regulate scTF and up-regulate B2M but without induction of PENK." (PMID 34911496, 2021). "Gleason 3 cancer cells show a degree of differentiation (scTF−B2Mhi) in the absence of PENK." (PMID 34911496, 2021). "In addition, several of these genes have not previously been reported as methylated in any type of cancer (KCNK4, SEPT5, PENK, BMP4, TAL1, PGF, SMARCB1 (INI1), FRZB (SFRP3), IRAK3 and MCM2)." (PMID 19493342, 2009). "Previously, we showed that cancer epithelial cells are CD10 negative, which would further suggest a link between PENK and CD10 as defects in enkephalinase activity may be associated with decreased PENK expression in cancer." (PMID 16343351, 2005).
tumor (26 papers, 2005 to 2025). "PENK expression negatively correlates with the tumor grade, and its high expression is linked to a favorable clinical outcome." (PMID 36361532, 2022). "Bioinformatic analysis revealed that PENK was downregulated in OS tumor samples compared with normal human osteoblasts." (PMID 32334633, 2020). "First, analysis with the Bioconductor software package revealed that PENK was downregulated in OS tumor cells compared with HOBs." (PMID 32334633, 2020). "The results showed that MNTX clearly boosted the anti-tumor effect of Doc in this clinical subject as well as in a GC cell line with a high level of PENK expression (Doc: 39.2 ± 5.8%, Doc/MNTX: 19.2 ± 2.1%)." (PMID 25853862, 2015). "We used two multiplex assays, namely Alb-Fam/WIF1-Vic and the NPY-Ned/PENK-Vic, to measure methylation of our three biomarkers in a set of 15 paired normal and tumor tissue samples." (PMID 24289328, 2013). "Down-regulation was seen for CNTN1, CXCL13, MAOB, PAGE4, PENK, SPOCK3 in CP compared to NP as well as for HSD17B2, SALL1, TRPA1 for tumor-associated bladder stromal cells compared to normal bladder." (PMID 19737398, 2009). "It is of note that PENK, which encodes the precursor peptide of the OPCML ligand enkephalin, was also found to be significantly hypermethylated in tumor tissue in our studies." (PMID 18616821, 2008). "Methylation status of PENK was not correlated with sex, age or stage, while it was associated with the tumor grade of BCa." (PMID 36403035, 2022). "Investigation of genomic and transcriptional data identified only 2 genes (ARFGEF1 and PENK) whose copy number and expression differentiated 'metastatic' from 'non-metastatic' tumours, neither of which have been previously implicated in malignancy." (PMID 21385341, 2011). "In the tumor samples analyzed there was down-regulation of PENK expression." (PMID 16343351, 2005). "Similarly, in one-third of our cases we observed amplification of this entire arm, while putative tumor suppressor genes, such as SOX17 and PENK, within this amplified chromosomal arm are methylated." (PMID 20300172, 2010). "Expression of stromal cell genes PENK and THY1/CD90 was minimal indicating that CD26 sorting was efficient enough to exclude CD90+ stromal cells, the other major cell type of tumor tissue." (PMID 20021671, 2009). "According to fold changes of expression level between non-tumor and tumor, representative target genes were CLIP2, TREM1 (miR-26a), SPOCK1 (miR-375), PENK, and ADAMTS16 (miR-1260)." (PMID 32313120, 2020).
kidney disease (4 papers, 2023 to 2025). "Further investigation of the relationship between PENK and the development and progression of kidney disease could enable these drugs to be utilized in the clinical management of kidney disease." (PMID 37935684, 2023). "Our study reveals the significant regulatory role of endogenous PENK-A in renal H2O2 production, positioning PENK as a potential drug target for kidney disease treatment." (PMID 37935684, 2023). "Proenkephalin A 119–159 (PENK) is a novel biomarker that reflects kidney function in patients with and without kidney disease, as well as in critically ill patients, independent of inflammation, age, or sex." (PMID 39456654, 2024).
neurodegenerative disease (3 papers, 2022 to 2025). A disorder of the central nervous system characterized by gradual and progressive loss of neural tissue and neurologic function. "In the present study, we investigated, for the first time, the levels of the PDYN- and PENK-derived peptides in patients with sCJD to thereby provide new insights into the possible mechanisms underlying the dysregulation of brain opioids in neurodegenerative diseases." (PMID 35216166, 2022). "Accordingly, CSF PENK and PDYN were within the normal range in ALS and AD, two neurodegenerative diseases with lack or low degree of striatal dysfunction/atrophy." (PMID 35737109, 2022). "Dysregulated metabolism and altered cerebrospinal fluid (CSF) levels of PENK and PDYN have been described in several neurodegenerative diseases." (PMID 35216166, 2022). "To the best of our knowledge, we detected MYL1 for the first time in the CSF of patients with neurodegenerative diseases, and together with MAP1B and PENK, it has not previously been linked to ALS." (PMID 40681694, 2025).
adenocarcinoma (2 papers, 2019 to 2021). A common cancer characterized by the presence of malignant glandular cells. "Of note, PENK signaling increased expression of the adenocarcinoma antigen AGR2 (electropherogram)." (PMID 34911496, 2021). "The up-regulation of AGR2 in LuCaP 70CR showed that PENK could also affect gene expression of adenocarcinoma cells." (PMID 34911496, 2021).
cardiovascular disease (1 paper, 2019). "Due to the links of enkephalins with cardiorenal status and existing evidence documenting the relationship of PENK and prognosis of cardiovascular disease, we examined the role of PENK in HFpEF." (PMID 30767059, 2019).
PENK also shares sentences with these, for which no sentence is quoted: ovarian carcinoma (4 papers); depression (3); meningioma (3); type 1 diabetes (3); hepatocellular carcinoma (2); Hyperglycemia (2); opioid dependence (2); type 2 diabetes (2); adenoma (1); albuminuria (1); alcohol dependence (1); allergic rhinitis (1); amyotrophic lateral sclerosis (1); bladder tumors (1); Cannabis use (1); carcinoids (1); COVID-19 (1); dry eye (1); Dystonia (1); Ewing sarcoma (1); follicular thyroid cancer (1); frontotemporal dementia (1); gastric cancer (1); head and neck cancer (1); heart-disease (1); Hematuria (1); heroin dependence (1); irritable bowel syndrome (1); keloid (1); kidney cancer (1).
A further 20 diseases each share a sentence with PENK in 1 paper.